CSRP3 (cysteine and glycine rich protein 3)
Diseases named in the same sentence as CSRP3 in open-access papers:
CSRP3 is named in the same sentence as 39 diseases in open-access papers, as found by Europe PMC text mining. Sharing a sentence is not in itself a finding about the gene and the disease. The quoted sentences say what the papers report.
cardiomyopathy (27 papers, 2011 to 2025). A disease of the heart muscle or myocardium proper. "Genetic mutations in the CSRP3 gene can result in cardiomyopathies, paralleled to human patients with downregulation of CSRP3 showing HF." (PMID 37837495, 2024). "Seven variants (41%) were detected in genes associated with cardiomyopathies including CSRP3, LAMA4, MYH6, MYBPC3, TNNI3, TNNI3K, and TNNT2." (PMID 39272661, 2024). "Three cases (34, 286 and 290) had one variant in a cardiomyopathy gene and one in a channelopathy gene (CSRP3 and TRPM4, PKP2 and ANK2, MYH7 and KCNH2, respectively)." (PMID 30615648, 2019). "Two interesting heterozygous deletions were found in genes (MYPN-patient XV and CSRP3-patient XVI) associated with a dominant cardiomyopathy." (PMID 30373198, 2018). "We found that many top associated a-DMSs, and their annotated gene were linked to diseases, such as SHANK2 (cg16069986 and cg16312514) which is related to autism, and CSRP3 (cg05895618) which is linked to cardiomyopathy." (PMID 28056824, 2017). "Moreover, the contribution of a proteo-toxic response to cardiomyopathy has been documented for pathogenic variants in CSRP3 and MYBPC3 through in vitro experiments and mouse models." (PMID 33637999, 2021). "Mutations in FHL150 and CSRP3 are known to cause cardiomyopathies." (PMID 34429479, 2021). "However, the underlying molecular mechanisms of CSRP3 mutation-induced cardiomyopathy are not well understood." (PMID 31406109, 2019). "Lastly, mutations in over 100 causal genes have been identified to engender cardiomyopathy in human patients, and our findings may only be specific to CSRP3 defects resulting in MLP deficiency." (PMID 31406109, 2019). "Although MYPN and CSRP3 may have a role in the observed cardiomyopathies, the primary genetic cause of the skeletal muscle disorder in these patients remains to be identified." (PMID 30373198, 2018). "Several pathogenic variants in CSRP3 have been shown to cause cardiomyopathies with AD inheritance." (PMID 29119312, 2017). "This has also been reported for other heterozygous cardiomyopathy gene models, such as Csrp3, Mybpc3, Myh7 and Ttn displaying phenotypes in homozygous settings only, whilst heterozygous animals showed no cardiac abnormalities." (PMID 40128237, 2025). "Among the four mechanosensing proteins, CSRP3 is considered a master regulator of muscle function and has aberrant primary expression patterns reported in human cardiomyopathy and secondary expression in skeletal muscle diseases." (PMID 34112090, 2021). "CSRP3 and NEBL bind actin and are important in maintaining muscle structure, with mutations causing cardiomyopathy in mammals." (PMID 31170930, 2019). "The newly generated Csrp3 KI mouse model reflects aspects of the human cardiomyopathy, especially in the homozygous setting." (PMID 30048712, 2018). "Several genetic studies have linked CSRP3 to cardiomyopathies; however, to our knowledge, no studies have examined its role in CAD." (PMID 39445733, 2025). "Muscle growth resulting from myostatin inactivation presumably creates an imbalance between the metabolic requirements of tissue cells and the previous perfusion capabilities of blood vessels, and CSRP3-encoded MLP may work to mediate this stress and reduce likelihood of cardiomyopathy." (PMID 25710176, 2015). "In this review we discuss selected examples of cardiomyopathy genes (TTN, FHL1, CSRP3, FLNC and PLN) which, based on their known biological functions and the (limited) functional work on the disease-causing pathogenic variants, have been shown to have important signalling functions in the heart." (PMID 29119312, 2017). "Also, telethonin was shown to physically partner with muscle LIM protein (MLP, CSRP3), hypothesized to be part of a macromolecular mechanosensor complex and to play a role in a subset of human cardiomyopathies." (PMID 23065501, 2013).
dilated cardiomyopathy (17 papers, 2013 to 2025). Cardiomyopathy which is characterized by dilation and contractile dysfunction of the left and right ventricles. "CSRP3 is a key regulator of sarcomeric structure with mutations that are linked to hypertrophic and dilated cardiomyopathy development in patients." (PMID 39041002, 2024). "Mutations in the CSRP3 gene have been linked to dilated cardiomyopathies (DCM) and hypertrophic cardiomyopathies (HCM)." (PMID 38556571, 2024). "CSRP3-deficient mice are characterized by the destruction of myocardial cell structure, dilated cardiomyopathy, and heart failure." (PMID 31979369, 2020). "Mutations in the CSRP3 gene have been suggested to cause heritable forms of hypertrophic cardiomyopathy and dilated cardiomyopathy in humans." (PMID 23537097, 2013). "Therefore, various myopathies caused by mutations of CSRP3, such as dilated cardiomyopathy, heart failure and muscular dystrophy, may be caused by insufficient autophagy." (PMID 31979369, 2020). "Mutations in cysteine and glycine-rich protein 3 (CSRP3)/muscle LIM protein (MLP), a key regulator of striated muscle function, have been linked to hypertrophic cardiomyopathy (HCM) and dilated cardiomyopathy (DCM) in patients." (PMID 38556571, 2024). "Evidencehas shown that CSRP3 mutations can result in both hypertrophiccardiomyopathy (HCM) and dilated cardiomyopathy (DCM) in patients." (PMID 39076905, 2022). "Specifically, in mice, reduced expression of CSRP3 leads to myocardial hypertrophy followed by dilated cardiomyopathy and heart failure." (PMID 29416668, 2018). "When crossed into the well-characterized Csrp3−/− mouse model of dilated cardiomyopathy, the Mg29 transgene was protective, increasing t-tubule organization and preserving both cardiac contraction and relaxation." (PMID 28706255, 2017). "Still more complex is the interpretation of the CSRP3 deletion identified in patient XVI, who presented with dilated cardiomyopathy and muscle weakness." (PMID 30373198, 2018). "The expression of NRAP is upregulated in mice models of dilated cardiomyopathy (DCM), such as CSRP3/MLP knockout mice and tropomodulin overexpressing transgenic mice." (PMID 28611399, 2017). "In the muscle LIM protein (MLP, also called Csrp3)-knockout mouse, a model for dilated cardiomyopathy, the levels of α-catenin, vinculin and F-actin were increased at the intercalated disc, which could well be an adaptive response in supporting the increased mechanical load of the failing heart." (PMID 32661904, 2020).
cardiac hypertrophy (14 papers, 2009 to 2025). "Downregulation of LIM protein CSRP3 has been reported in human undergoing pathogenic cardiac hypertrophy." (PMID 19232135, 2009). "Among them, Csrp3, Pdlim5, Sorbs2, Rcan1, and Acta1, which were related to cardiac hypertrophy and remodeling, were upregulated and modified by at least one active histone mark." (PMID 33330655, 2020). "Our study also provides insights into the molecular mechanism of aberrant glycosylation in cardiac hypertrophy, particularly by highlighting the significance of O-glycosylation changes on CSRP3." (PMID 27281159, 2016). "We hypothesized that circ-0001283 regulated cardiac hypertrophy via MYL3 or CSRP3." (PMID 40007621, 2025). "In our study, we found that SLC25A5 is positivelycorrelated with CSRP3, indicating that SLC25A5 might alsoparticipate in the process of myocardial hypertrophy." (PMID 39076905, 2022).
heart failure (13 papers, 2008 to 2025). Inability of the heart to pump blood at an adequate rate to meet tissue metabolic requirements. "One of the key proteins that are present in the Z-disc of cardiac tissues, CSRP3, has been implicated in dilated and hypertrophic cardiomyopathy leading to heart failure." (PMID 37065494, 2023). "The mutations of various genes encoding the proteins around the Z-disc, such as ANKRD1, DES, FLNC and CSRP3, are known to cause abnormal responses to mechanical stress, resulting in heart failure." (PMID 39195917, 2022). "At 12–15 weeks of age, Csrp3−/− mice expressing Mg29 had significantly improved t-tubule integrity compared to control Csrp3−/− mice expressing only the single tTA transgene, including a reduction in longitudinal t-tubule elements that is a hallmark of heart failure." (PMID 28706255, 2017). "Functional analysis of Csrp3 knock-in animals (Csrp3Trp4Arg/+) and (Csrp3Trp4Arg/Trp4Arg) showed an age-and gene dosage-dependent HCM and heart failure, characterized by a nearly complete loss of contractile function under catecholamine-induced stress." (PMID 39554508, 2024). "A significant reduction in CSRP3 protein levels was reported in dilated and ischemic cardiomyopathy patients leading to heart failure." (PMID 37065494, 2023). "Overexpression, aberrations in oligomerization and nuclear accumulation of CSRP3 have been detected in animal models of MI and human heart failure and are thought to stimulate ribosomal protein synthesis in the nucleolus, promoting LV hypertrophy." (PMID 35563680, 2022). "To investigate if the induction of Mg29 that normally occurs in the setting of heart failure due to Csrp3 deletion was truly compensatory, we crossed Sypl2−/− mice into the Csrp3−/− background and assessed t-tubule organization and cardiac performance." (PMID 28706255, 2017). "The induction of Mg29 expression observed in Csrp3−/− mice was clearly of functional importance as deletion of the Sypl2 gene further reduced t-tubule structure and organization and it worsened heart failure in Csrp3−/− mice." (PMID 28706255, 2017). "Additionally, CSRP3 and SLMAP that were identified as possibly downregulated are known calcium handling modulators and are dysregulated in heart failure, with downregulation of CSRP3 in a Ryr2 KO mouse model." (PMID 39041002, 2024). "Consistent with our hypothesis, it is not surprising that Csrp3/Mlp nulls have a strong cardiac phenotype and Csrp3/Mlp mutations are associated with heart failure in humans." (PMID 18713466, 2008).
hypertrophic cardiomyopathy (13 papers, 2008 to 2025). "CSRP3 deficient human ES-cell derived cardiomyocytes display defects in calcium handling with increased cytosolic calcium, elevated ROS levels showing a hypertrophic cardiomyopathy phenotype." (PMID 39041002, 2024). "In line with this hypothesis, the morphological and clinical picture of dilated cardiomyopathy in humans is associated with altered Csrp3/Mlp expression and Csrp3/Mlp mutations were found in families suffering from dilated as well as from hypertrophic cardiomyopathy." (PMID 18713466, 2008). "Cysteine and glycine-rich protein 3 (CSRP3) is one of key proteins implicated in dominant dilated cardiomyopathy (DCM) and hypertrophic cardiomyopathy (HCM)." (PMID 35241752, 2022). "Muscle LIM protein (MLP, CSRP3) is a key regulator of striated muscle function, and its mutations can lead to both hypertrophic cardiomyopathy (HCM) and dilated cardiomyopathy (DCM) in patients." (PMID 31406109, 2019). "Mutations in the human CSRP3 gene have subsequently been associated with autosomal dominant DCM and hypertrophic cardiomyopathy (HCM)." (PMID 30048712, 2018). "Cysteine and glycine rich protein 3 (CSRP3) encodes Muscle LIM Protein (MLP), a well-established disease gene for Hypertrophic Cardiomyopathy (HCM)." (PMID 30048712, 2018). "Moreover, mutations in CSRP3, a member of the CSRP family containing the LIM domain, cause hypertrophic cardiomyopathy, a genetic cardiac disease, and the most common cause of sudden cardiac death." (PMID 36836780, 2023). "Mutations in CSRP3 have been associated with myofibrillar disarray and hypertrophic cardiomyopathy in humans, however, the coding sequence of CSRP3 in MFM WB did not contain any variants associated with the MFM phenotype." (PMID 34112090, 2021). "However, modern analysis is revealing that the heterogeneity in hypertrophic cardiomyopathy may be attributed to defects in secondary genes like cysteine and glycine rich protein 3 (CSRP3)." (PMID 35078412, 2022).
muscular dystrophy (4 papers, 2020 to 2025). Muscular dystrophy (MD) refers to a group of more than 30 genetic diseases characterized by progressive weakness and degeneration of the skeletal muscles that control movement. "Here we showed that when CSRP3 is knocked down, the myogenic gene expression is down-regulated and the muscular dystrophy protein expression is up-regulated." (PMID 31979369, 2020). "Consistent implication of MYBPC3, CSRP3, CAV3, TCAP, and TTN across multiple pathways highlights convergent mechanisms, while moderate enrichment of muscular dystrophy pathways (involving CAV3 and TTN) further suggests overlapping pathophysiological networks." (PMID 41153379, 2025). "CSRP3 is a plausible EDMD candidate gene because Csrp3 is a mechanosensitive transcription regulator in muscle and cofactor for MyoD1, and also binds LC3 and promotes autophagy as a mechanism of protection against muscular dystrophy." (PMID 37936983, 2023).
Insulin resistance (2 papers, 2012 to 2021). Increased resistance towards insulin, that is, diminished effectiveness of insulin in reducing blood glucose levels. "CSRP3 knockout mice fed a high-fat diet had reduced insulin resistance and glucose tolerance, increased skeletal muscle inflammation, and impaired insulin signaling." (PMID 33677919, 2021).
atrial fibrillation (1 paper, 2017). A disorder characterized by an electrocardiographic finding of a supraventricular arrhythmia characterized by the replacement of consistent P waves by rapid oscillations or fibrillatory waves that vary in size, shape and timing and are accompanied by an irregular ventricular response. "This extended gene network contained a number of transcription factors (Tbx5, Hand2, Fhl2, and Gata4) and ion/calcium handling genes (Ank2, Cacna2d2, Scn5a, Kcnd2, Kcnj5, Myoz2, Casq2, Csrp3, and Gja3) of interest in the context of atrial fibrillation." (PMID 28720711, 2017).
chronic heart failure (1 paper, 2022). "Considering that CSRP3 is significantly downregulated in chronic human heart failure, CSRP3 could be a therapeutic target for chronic heart failure as well as for MI." (PMID 39195917, 2022).
dilatation (1 paper, 2018). "These mice were found to have a similar level of LV dilatation and reduced fractional shortening to Csrp3-/- mice at 2 months of age, indicating that the Csrp3 C58G allele cannot functionally compensate for the loss of the Csrp3 WT allele on the Csrp3 null background." (PMID 30048712, 2018).
Emery-Dreifuss muscular dystrophy (1 paper, 2023). Emery-Dreifuss muscular dystrophy (EDMD) is characterized by muscular weakness and atrophy, with early joint contractures and cardiomyopathy. "CSRP3, LMCD1, ALDOA, PERM1: candidate genes for Emery-Dreifuss muscular dystrophy that may also provide insight into frailty-related muscle weakness?" (PMID 37936983, 2023).
endocardial fibroelastosis (1 paper, 2021). Endomyocardial fibroelastosis is a cause of unexplained childhood cardiac insufficiency. "For example, genes (e.g., TAZ, NEX, MYH7, and CSRP3) have been demonstrated to involve the development of endocardial fibroelastosis." (PMID 34469078, 2021).
facioscapulohumeral muscular dystrophy (1 paper, 2020). An autosomal dominant disorder affecting the skeletal muscles of the face, scapula, and upper arm. "CSRP3 expression levels and intracellular localization are associated with many skeletal myopathies, such as nemaline myopathy, facioscapulohumeral muscular dystrophy (FSHD), and limb-girdle muscular dystrophy type 2B." (PMID 31979369, 2020).
Myocardial fibrosis (1 paper, 2025). "This study shows that downregulated CSRP3 expression may be closely related to myocardial fibrosis and structural remodeling in AF patients." (PMID 41257259, 2025).
Stroke (1 paper, 2025). Sudden impairment of blood flow to a part of the brain due to occlusion or rupture of an artery to the brain. "In particular, on post-stroke days 3 and 9, Cysteine and glycine-rich protein 3 (Csrp3) was included in the analysis due to its expression meeting the differential screening criteria, and its interaction with the differentially expressed thin filament proteins was predicted in both cases." (PMID 41226396, 2025). "However, on post-stroke day 6, Csrp3 expression did not meet the criteria and was therefore excluded from the differentially expressed protein set at this time point, resulting in no predicted interaction between Csrp3 and the differentially expressed thin filament proteins." (PMID 41226396, 2025).
cardiac disease (5 papers, 2010 to 2024). "Amongst these proteins is Muscle LIM Protein (MLP/CSRP3), which has long been associated with cardiac disease." (PMID 30742931, 2020). "As several heart disease-related mutations have been observed in the same domain in CSRP3, it is tempting to suggest that this bear-specific substitution may confer adaptive advantage for bear heart during biological processes such as hibernation." (PMID 20338065, 2010). "Our study highlights the critical role of Csrp3 in zebrafish heart development and regeneration, and provides a valuable animal model for further functional exploration which will facilitate the understanding of the molecular pathogenesis of CSRP3-related human cardiac diseases." (PMID 38556571, 2024). "Our study highlights the critical role of Csrp3 in both zebrafish heart development and regeneration, and provides a valuable animal model for further functional exploration that will shed light on the molecular pathogenesis of CSRP3-related human cardiac diseases." (PMID 38556571, 2024).
myopathy (5 papers, 2014 to 2025). A disease of the muscle in which the muscle fibers do not function properly. "Additionally, upregulation of CSRP3 has been associated with altering muscle fiber types from fast to slow, autophagy in muscle cells, and repair mechanism for myofibers, making it a potential molecular marker for myopathies." (PMID 40841884, 2025). "To investigate the mechanism of disease in CSRP3 myopathy, we performed siRNA-mediated CSRP3 knockdown in chicken primary myoblasts." (PMID 31979369, 2020).
autosomal dominant disease (1 paper, 2024). Autosomal dominant form of disease. "For example, CSRP3 was previously curated for only autosomal dominant disease, but based on available evidence considered to have a semi-dominant inheritance pattern, meaning heterozygous variants can have an intermediate phenotype." (PMID 39132495, 2024).
cardiovascular diseases (1 paper, 2025). "We selected 2 proteins, MYL3 and cysteine and glycine-rich protein 3 (CSRP3), which are abundantly expressed in hearts and are closely associated with cardiovascular diseases, for further investigation." (PMID 40007621, 2025).
CSRP3 also shares sentences with these, for which no sentence is quoted: myocardial infarction (3 papers); Obesity (2); abdominal aortic aneurysm (1); actinomycosis (1); autism (1); autism spectrum disorder (1); breast carcinoma (1); channelopathy (1); COVID-19 (1); Danon disease (1); diabetes (1); dominant dilated cardiomyopathy (1); familial atrial fibrillation (1); hypertrichotic osteochondrodysplasia (1); hypertrophy (1); Malan syndrome (1); Norum disease (1); pulmonary hypertension (1); renal carcinoma (1); skeletal muscle disorder (1).